CRH (corticotropin releasing hormone)
Diseases named in the same sentence as CRH in open-access papers (continued):
Sharing a sentence is not in itself a finding about the gene and the disease.
alopecia (3 papers, 2024 to 2025). Hair loss usually from the scalp. "The aim of the study is to elucidate the key mechanisms of alopecia caused by CRH and provide potential new targets for the treatment of stress-related hair loss." (PMID 40219757, 2025). "Particular emphasis is placed on the role of the hypothalamic–pituitary–adrenal axis hormones (corticotropin-releasing hormone, adrenocorticotropic hormone (ACTH), cortisol) in stress-induced alopecia." (PMID 38540126, 2024). "Another contrary study showed that corticotropin-releasing hormone inhibited autophagy of hair follicle dermal papilla cells and promoted apoptosis by suppressing PTEN in the PI3K/AKT/mTOR signaling pathway, resulting in blocked hair follicle regeneration and triggering stress-induced alopecia." (PMID 40665727, 2025).
alopecia areata (3 papers, 2021 to 2022). Loss of scalp and body hair involving microscopically inflammatory patchy areas. "We also showed that CRH enhances tryptase expression within individual hM-MCs, mirroring a phenomenon we previously observed in perifollicular human CT-MCs (hCT-MCs) alopecia areata skin lesions." (PMID 33803422, 2021).
atherosclerosis (3 papers, 2015 to 2024). A disease characterized by the build-up of fatty material and calcium deposition in the arterial wall resulting in partial or complete occlusion of the arterial lumen. "Additionally, the upregulation of vascular cell adhesion molecule-1 by CRH has been shown to promote atherosclerosis progression in LDL receptor-deficient mice." (PMID 39742022, 2024). "Our study affirmed the role of ABCA1 in the atherogenic process and verified a mechanism by which CRH as a stress hormone accelerates macrophage foam cell formation, which is a pivotal step in atherosclerosis." (PMID 26110874, 2015). "We performed assays to verify the effect of CRH on macrophage foam cell formation, the initial critical step in atherosclerosis." (PMID 26110874, 2015). "In the current study, we revealed that CRH promotes macrophage foam cell formation, which is the initial critical stage of atherosclerosis." (PMID 26110874, 2015). "Our current study using murine peritoneal macrophages provides this explanation and shows how CRH promotes macrophage foam cell formation, which is the initial and critical step in the development of atherosclerosis." (PMID 26110874, 2015). "Our current study aimed to verify the role of CRH in macrophage foam cell formation, the initial critical stage of atherosclerosis." (PMID 26110874, 2015). "The CRH-activated pathway promotes macrophage foam cell formation, which is a critical step in atherosclerosis." (PMID 26110874, 2015). "We conclude that activation of this pathway by CRH accelerates macrophage foam cell formation and may promote stress-related atherosclerosis." (PMID 26110874, 2015). "CRH exists widely throughout brain and peripheral tissues, regulating endocrine, behavioral and immune responses to stress, and thus could be a candidate molecule providing the mechanistic explanation for the psychological etiology of atherosclerosis." (PMID 26110874, 2015).
atopic dermatitis (3 papers, 2021 to 2026). "Atopic dermatitis and nasal allergies are exacerbated by psychological stress, and the activation of mast cells by CRH in human skin and nasal mucosa may be a key mechanism." (PMID 35955675, 2022).
bipolar disorder (3 papers, 2009 to 2025). A disorder of the brain that causes unusual shifts in mood, energy, activity levels and the ability to carry out day-to-day tasks. "In 114 depressed inpatients suffering from unipolar or bipolar depression (sample 1) the DEX/CRH test was performed at admission and shortly before discharge." (PMID 19177168, 2009).
chorioamnionitis (3 papers, 2012 to 2024). A morphologic finding indicating inflammation of the fetal sac membranes. "Recent data have reported that, in human placentas from women with PPROM and chorioamnionitis, inflammatory events are associated with changes to the CRH-related mechanism of labor, such as increased CRH, UCN 2, and CRH-R1 mRNA expression and decreased UCN 3 and CRH-R2 expression." (PMID 22028729, 2012).
cognitive decline (3 papers, 2023 to 2025). "We show that CRH is a promising biomarker for Lewy body disease and atypical PS and its association with inflammation and cognitive decline." (PMID 39605973, 2024). "According to the CRH, individuals with higher cognitive reserve possess a greater ability to resist cognitive decline." (PMID 37881361, 2023). "Therefore, the downregulation of VGF, NEUROD6, KCNF1, KCNE5, CRH, and RPH3A may contribute to the cognitive decline observed in elderly individuals with AD." (PMID 39834440, 2025).
colon cancer (3 papers, 2019 to 2024). "Our results provide evidence to support a critical role for the CRH/CRF1 signaling in colon cancer progression and suggest its potential utility as a new therapeutic target for CAC." (PMID 38616821, 2024). "Taken together, CRH/CRF1 signaling promotes human colon cancer cell proliferation via NF-κB/IL-6/STAT3 and tumor angiogenesis via NF-κB/VEGF signaling pathway." (PMID 38616821, 2024). "Opposed to CRHR2/Ucn2 signaling, CRHR1 activation by CRH promoted selectively colon cancer cell proliferation through an IL-6/JAK2/STAT3-depended mechanism and induced angiogenesis via VEGF up regulation." (PMID 31614860, 2019). "Stress, inflammation and colon cancer are highly related, forming a CRH-system driven crosstalk." (PMID 38616821, 2024). "CRH enhances colon cancer cell proliferation, promoting colony formation." (PMID 38616821, 2024). "However, peripheral effects of the CRH system in colon cancer remains elusive." (PMID 33494263, 2021). "Furthermore, the mRNA level of UCN III, a CRHR2-specific peptide among the CRH family, was dramatically reduced in colon cancer tissues compared to that of controls; however, the level of CRH, a CRHR1-restricted ligand, was not changed in these tissues." (PMID 33494263, 2021).
congestive heart failure (3 papers, 2020 to 2026). Failure of the heart to pump a sufficient amount of blood to meet the needs of the body tissues, resulting in tissue congestion and edema. "The IPTW-HRs for haemorrhagic stroke in the CH group was 0.424 (95% CI: 0.188–0.957), for congestive heart failure (CHF) in the RH group was 0.260 (95% CI: 0.088–0.762), and for ischaemic heart disease in the CRH group was 0.544 (95% CI: 0.317–0.934)." (PMID 31996695, 2020).
delirium (3 papers, 2021 to 2025). A disorder characterized by confusion; inattentiveness; disorientation; illusions; hallucinations; agitation; and in some instances autonomic nervous system overactivity. "In the present study, our data also indicate that lower IGF‐1 and CRH levels are tightly associated with postoperative delirium." (PMID 37137534, 2023). "Lower insulin‐like growth factor‐1 (IGF‐1, p = .024) and corticotropin‐releasing hormone (CRH, p = .005) levels were closely associated with postoperative delirium and with high levels of blood glucose (GLU, p = .023) after surgery." (PMID 37137534, 2023). "The data suggest that neuropsychiatric syndromes (i.e., delirium) after peripheral trauma might be at least in part due to the activation of the hippocampal CRH/NF-κB/BDNF pathway, which results in a dramatic loss of synaptic contacts." (PMID 32051550, 2021). "In summary, our study provides a novel model of acute physical stress responses and delirium as well as molecular insights into posttraumatic (especially synaptic) changes in the brain that are initiated by the elevation of hippocampal CRH levels." (PMID 32051550, 2021). "Here, we propose a novel mechanistic concept of the development of delirium based on the idea of hippocampal stress response triggered by an elevation of posttraumatic interneuronal CRH production and release." (PMID 32051550, 2021). "Subsequent analysis indicated that serum potassium (OR: 0.311, 95% CI 0.103–0.935), sodium (OR: 0.991, 95% CI 0.983–1.000), CRH (OR: 0.964, 95% CI 0.936–0.994), and GLU (OR: 1.654, 95% CI 1.137–2.406) levels in the perioperative period were independent risk factors for delirium." (PMID 37137534, 2023). "The results showed that compared to the delirium group, patients without delirium had a higher secretion of IGF within 72 h of surgery, as well as CRH after 72 h of surgery (116.55 ± 101.79 vs." (PMID 37137534, 2023).
dermatitis (3 papers, 2015 to 2025). An inflammatory process affecting the skin. "We evaluated dermatitis score and histology analysis of dorsal skin lesions, meanwhile, serum corticosterone (CORT), adrenocorticotropic hormone (ACTH), corticotropin-releasing hormone (CRH) and inflammatory cytokines were determined by ELISA." (PMID 25658752, 2015).
endothelial dysfunction (3 papers, 2022 to 2025). In vascular diseases, endothelial dysfunction is a systemic pathological state of the endothelium (the inner lining of blood vessels) and can be broadly defined as an imbalance between vasodilating and vasoconstricting substances produced by (or acting on) the endothelium. "Mental stress induces endothelial dysfunction through increased activity of the sympathetic nervous system, release of corticotropin-releasing hormone from the hypothalamus, inhibition of nitric oxide (NO) synthesis by cortisol, and increased levels of pro-inflammatory cytokines." (PMID 35956022, 2022).
glioma (3 papers, 2011 to 2024). A benign or malignant brain and spinal cord tumor that arises from glial cells (astrocytes, oligodendrocytes, ependymal cells). "Furthermore, TMEFF2 inhibited the production of adrenocorticotropic hormone (ACTH) in response to CRH (corticotropin releasing hormone) stimulation in AtT20 glioma cells; this action was demonstrated to be the result of TMEFF2-imparted action at multiple levels of CRHR1 signalling." (PMID 33371267, 2020).
infantile spasms (3 papers, 2011 to 2026). A rare epilepsy syndrome characterized by onset of epileptic spasms in infants between 2 and 12 months of age, and rarely up to 24 months. "Finally, an excess in CRH has been hypothesized to underlie West syndrome, in which seizures during infancy play an important role, and CRH has been found to play a role in the increased susceptibility to seizures in shigellosis." (PMID 21858011, 2011). "High-dose ACTH treatment was considered to contribute to the normal adaptation of the hypothalamic-pituitary-adrenal axis by regulating the release of corticotropin-releasing hormone, resulting in improvement of the patient's infantile spasms and sleep disturbances." (PMID 33114276, 2020).
memory impairment (3 papers, 2019 to 2023). "A possible role for the hippocampal corticotropin-releasing hormone (CRH) was suggested in glutamatergic synaptic dysfunction and memory impairment in MS rats." (PMID 37443769, 2023). "Additionally, IL-1β participates in the induction of memory impairment, as well as in the release of CRH." (PMID 37189795, 2023).
Psychological distress (3 papers, 2018 to 2026). "In addition CRH is known to be associated with psychological distress, conditions that are common among the elderly and that we recently identified as associated with GI symptoms and an increased intestinal permeability." (PMID 30194322, 2018). "Thus, the emotional dysregulation occurring during the withdrawal days here reported, might result from a between-system—rather than a within-system—interference, in which CRH may act as a contextual signal, gating the NAc neural maladaptation associated to binge-like alcohol exposure." (PMID 34572345, 2021).
rheumatoid arthritis (3 papers, 2016 to 2023). A chronic, systemic autoimmune disorder characterized by inflammation in the synovial membranes and articular surfaces. "For example, in rheumatoid arthritis, both UCN1 and CRH expression levels were increased in intestinal macrophages of ulcerative colitis patients, suggesting a pro-inflammatory role." (PMID 35276788, 2022).
seborrhea (3 papers, 2020 to 2026). "A study conducted on seborrheic patients showed that increased ghrelin levels in the blood may induce overexpression of CRH in sebaceous glands, and then CRH plays its role in inducing lipogenesis in sebocytes and the progression of seborrhea." (PMID 32565790, 2020).
skin cancer (3 papers, 2021 to 2025). "Recently, CRH is expressed in skin cancers, where its expression appears to correlate with the degree of malignancy." (PMID 40917468, 2025). "In line with the current results, it was previously reported that the expression of CRH was upregulated in skin cancer, compared to cutaneous premalignant lesions." (PMID 37382757, 2024). "However, the role of the CRH-POMC axis in skin tumors is largely unknown." (PMID 34068618, 2021). "To determine whether CRH exerts a functional effect on nonmelanoma skin cancer cells, as has been described for various human skin cells, we performed functional in vitro assays using the epidermoid carcinoma cell line A431." (PMID 40917468, 2025).
Addison disease (2 papers, 2020 to 2023). "AI is attributed to a failure of cortisol production by the zona fasciculata of the adrenal cortex (primary AI or Addison disease) or by a deficiency of adrenocorticotropin hormone (ACTH, secondary AI) and/or corticotropin-releasing hormone (CRH, tertiary AI)." (PMID 32555949, 2020).
Arthritis (2 papers, 2019 to 2020). Inflammation of a joint. "Although we were unable to evaluate these cells with IHC due to the low sensitivity of the CRH antibody, this result suggested that CRH neurons in the pPVN are activated by acute mono-arthritis." (PMID 32117068, 2020). "In contrast, chronic nociceptive stimuli, such as adjuvant arthritis, downregulate CRH neuronal activity; in these conditions, AVP neurons in the pPVN are more dominant and play crucial roles in HPA axis activation." (PMID 32117068, 2020). "We conducted ISH to investigate activation of the HPA axis caused by acute mono-arthritis based on gene expression levels of HPA axis-related peptides including AVP hnRNA and CRH mRNA in the pPVN and POMC mRNA in the AP." (PMID 32117068, 2020). "In addition, the HPA axis is activated by both AVP and CRH in acute mono-arthritis with a distinct pattern compared to that in chronic multiple-arthritis." (PMID 32117068, 2020). "Further, AVP, not corticotropin-releasing hormone (CRH), predominantly activates the HPA axis in chronic multiple-arthritis, but the participation of AVP in HPA axis activation in acute mono-arthritis remains unknown." (PMID 32117068, 2020).
Atrophy (2 papers, 2017 to 2024). Any weakening or degeneration, especially through lack of use. "Because we found that muscle atrophy markers were increased in the CRH‐Tg mice, these results suggest that GC‐induced muscle atrophy can be induced at the gene expression level in this mouse model." (PMID 30283880, 2017). "Rodent studies show that neonatal rats treated with dexamethasone show reduced GCR in response to cold and restraint stress later in life, while mice subjected to prolonged low-dose corticosterone exposure show suppressed GCR, adrenal atrophy, and decreased CRH mRNA levels in the PVN." (PMID 39607018, 2024).
autism spectrum disorder (2 papers, 2017 to 2018). A spectrum of developmental disorders that includes autism, and Asperger syndrome. "The use of serotonin specific reuptake inhibitors (SSRIs) has been weakly associated with delayed motor development and elevated corticotropin-releasing hormone levels and has been proposed to be a risk for autism spectrum disorder." (PMID 29891804, 2018).
autoimmune disease (2 papers, 2021 to 2023). A disorder resulting from loss of function or tissue destruction of an organ or multiple organs, arising from humoral or cellular immune responses of the individual to their own tissue constituents. "Corticotropin-releasing hormone (CRH) and AVP of the hypothalamic paraventricular parvocellular neurons play an important role in coordinating hypothalamic-pituitary-adrenal axis activity during stress, inflammation, and autoimmune diseases." (PMID 34926704, 2021).
breast tumor (2 papers, 2023 to 2025). "In our study, we observed a hypofunctional HPA axis in the breast tumor-induced fatigue model, characterized by reduced CRH peptide expression in the hypothalamus and lower serum levels of CRH and cortisol." (PMID 40993108, 2025).
cardiac hypertrophy (2 papers, 2014 to 2024). "For example, a recent GWAS found evidence for enrichment of risk SNPS in the following pathways: corticotropin-releasing hormone signaling, cardiac β-adrenergic signaling, phospholipase C signaling, glutamate receptor signaling, endothelin 1 signaling, and cardiac hypertrophy signaling." (PMID 25202283, 2014). "Beyond biochemical alterations (increased CRH, ACTH, and cortisol levels), abnormal stress also causes anatomical changes in HPA axis components, such as adrenal hypertrophy and increased pituitary gland volume observed in both rodents and humans." (PMID 39193580, 2024).
chronic fatigue syndrome (2 papers, 2021 to 2025). "Auriculotherapy modulates excessive secretion of corticotropin-releasing hormone, cortisol hormone, and plasma adrenocorticotropic through the regulation of hypothalamic-adrenal axis function, which is expressed as one of the mechanisms by which auriculotherapy affects chronic fatigue syndrome." (PMID 34565433, 2021). "Decreased CRH levels in chronic fatigue conditions such as CRF and chronic fatigue syndrome have been reported, suggesting that HPA axis hypofunction may contribute to fatigue symptoms through impaired stress adaptation, insufficient cortisol production, and sustained inflammation." (PMID 40993108, 2025).
Cocaine Addiction (2 papers, 2018 to 2024). "Therefore, CRH neurons in the vBNST should be critical for the process of cocaine addiction, particularly stress-induced cocaine relapse." (PMID 38681523, 2024). "Therefore, the excitability of CRH neurons in the vBNST are crucial for cocaine addiction, specifically stress-induced drug craving and relapse." (PMID 38681523, 2024). "Given that cocaine acts as a type of Sig-1Rs agonist, and the dramatic role of Sig-1Rs played in intrinsic excitability of neurons as well as cocaine addiction, we employ BD1063 a canonical Sig-1Rs antagonist to block the effects of cocaine, and significantly recover the excitability of CRH neurons." (PMID 38681523, 2024). "Given the relation of CRH neurons in the vBNST and dopamine neurons in the VTA as well as their essential roles in cocaine addiction, we propose that a single exposure of cocaine may also cause the alteration of intrinsic plasticity in CRH neurons of the vBNST." (PMID 38681523, 2024).
endometrial carcinoma (2 papers, 2012 to 2025). A malignant tumor arising from the epithelium that lines the cavity of the uterine body. "CRH expression has been found in other cancer types such as breast, ovarian, and endometrial cancers." (PMID 40917468, 2025). "Accordingly, CRH was found to induce cAMP in human endometrium via CRHR1 triggered protein-kinase A (PKA) and we recently found that Syn1 is induced via the cAMP pathway in endometrial carcinoma." (PMID 22971074, 2012).
endotoxemia (2 papers, 2018 to 2021). "LPS-induced endotoxemia causes HPA axis activation through the parvocellular neurons activation that synthesize and secrete CRH in the hypothalamus." (PMID 33430014, 2021).